CD44 (CD44 molecule (IN blood group))
Diseases named in the same sentence as CD44 in open-access papers (continued):
Sharing a sentence is not in itself a finding about the gene and the disease.
cervical carcinoma (continued). "Furthermore, resveratrol's ability to mitigate the treatment resistance and metastatic effects of CD44 allows for opportunistic chemo‐sensitizing effects of cervical cancer cells to carboplatin." (PMID 40888184, 2025). "However, abnormally enhanced MDR1 expression levels, observed in CD44‐positive cervical cancer cells, exacerbate this resistant phenomenon and favor the formation of treatment‐resistant cancer cells, including CSCs." (PMID 40888184, 2025). "Moreover, CD44's well‐known three‐domain structure facilitates the formation of structural CD44 isoforms, which favor metastatic effects as observed in cervical cancer cells." (PMID 40888184, 2025). "This could therefore suggest a corresponding reduction in CD44 expression as well as enhanced chemo‐sensitivity within cervical cancer cells." (PMID 40888184, 2025). "Further investigations into the role of ICI therapy on CD44’s EMT-inducing potential within cervical cancer, could show promising therapeutic potential." (PMID 38816670, 2024). "Interestingly, they observed both the CaSki and HeLa cervical cancer cell lines with corresponding high levels of CD44 in conjunction with the high CTLA-4 levels." (PMID 38816670, 2024). "Combined with the existing reports and GBP1-regulated AS events, we finally obtained a regulatory pathway, that is, GBP1 and HNRNPK binding, through the A3SS alternative splicing form, regulate the expression of CD44 protein, and finally play a cancer-promoting role in cervical cancer." (PMID 38167153, 2024). "Furthermore, CD44, as the specific cell adhesion molecule, is proven to increase the migration and invasion of cervical cancer." (PMID 37735483, 2023). "In addition, some specific biomarkers (such as peritoneal HPV-DNA, CEA, SCC-Ag, CD44) are helpful to identify early cervical cancer, make the best treatment plan for patients and improve the prognosis." (PMID 36476597, 2022). "Some markers such as E-cadherin, Ki67, CEA, and CD44 were reported to server detecting invasive forms of cervical cancer, which might be useful in evaluation and monitoring of treatments of patients with evaluation and monitoring of treatments." (PMID 36536343, 2022). "Concerning the relationship between CD24 expression and the EMT features, heterogeneity of cervical cancer cells has been recently reported: only cells having CD44 (+) CD24 (-) phenotype exhibited mesenchymal traits and attained invasive, migratory and spreading abilities." (PMID 32899940, 2020). "Moreover, tissue sections of invasive cervical cancer expressed high levels of CD44 (by flow Cytometry and direct IF) making it highly unlikely to be a cancer stem cell marker." (PMID 29609538, 2018). "Other groups have reported an increase of the expression of CD44 or ALDH1 for cervix cancer SFC." (PMID 27901496, 2017). "We identified HeLa (cervix carcinoma) and H4 (neuroglioma) cells to express CD44 at detectable levels in Western blot analysis and could also confirm the specific cleavage fragment of CD44 at 37 kDa after transient expression of meprin β in these two cell lines." (PMID 36876041, 2023). "Compared to older patients, younger cervical cancer patients often exhibit the following characteristics: immune deficiency; tobacco smoking; high serum hormone levels; cervical erosions; HPV16 infection; and high levels of survivin, cyclooxygenase 2, matrix metalloproteinase and CD44 expression." (PMID 32033340, 2020). "The upregulated ligand receptor pairs in the cervical cancer group were SPP1 − CD44, FN1 − SDC4, FN1 − SDC1, FN1 − CD44, CD99 − CD99, and the downregulated ligand receptor pairs were PPIA – BSG, LGALS9 − P4HB, LGALS9 − CD44." (PMID 41384115, 2025).
cervical carcinoma (continued). "In cervical cancer, TCF4 silencing suppresses proliferation and CSC characteristics by downregulating CD44 and Wnt/β-catenin pathway genes, such as β-catenin and c-Myc." (PMID 40290725, 2025). "Thus, this review aims to evaluate whether resveratrol treatment could potentially enhance the chemo‐sensitivity of cervical cancer cells to the chemotherapeutic drug, carboplatin, by mitigating the pathological effects of CD44‐induced metastasis and chemoresistance within cervical cancer patients." (PMID 40888184, 2025). "In cervical cancer, GBP1, after binding to HNRNPK, regulates CD44 protein expression through alternative splicing at the 3′ splice site, ultimately playing a cancer-promoting role." (PMID 40018406, 2025). "That is, GBP1, after binding with HNRNPK, regulates the expression of CD44 protein through A3SS alternative splicing form, and finally plays a cancer-promoting role in cervical cancer." (PMID 38167153, 2024). "This study aims at formulation of NDV loaded thiolated chitosan nanoparticles, surface functionalized with HA for CD44 targeted delivery and sustained release of oncolytic NDV in cervical cancer cells." (PMID 37283735, 2023). "Tumorsphere formation assays and immunofluorescence staining of cervical cancer stem cell markers (CD133 and CD44) indicated that CENPK knockdown reduced stemness of HeLa and SiHa cells." (PMID 35418160, 2022). "The expression of markers of the immune system such as CD95, MICA/B, CD39, CD73, NKp30, NKp46, CD44, CD24, NKG2A, and CTLA-4 was analysed by flow cytometry on cervical cancer cells INBL (HPV 18, stage IVB), HeLa (HPV 18), CaSki (HPV 16), and C33A (HPV-)." (PMID 31198791, 2019). "The cell surface expression of CD74 and CD44 was appraised in CAMA-1, MDA-MB-231, MDA-MB-435, Raji and cervical cancer HeLa cells." (PMID 29190904, 2017). "Emerging evidence suggests that the anticancer effects of resveratrol in cervical cancer may surpass HPV status, yet its efficacy could be modulated by the presence of the CSC marker, CD44." (PMID 40888184, 2025). "While CD44 is naturally expressed at homeostatic levels throughout the body, facilitating cell–cell integrity and cell‐extracellular matrix (ECM) communication, its expression is significantly elevated within the TME, including the cervical cancer TME." (PMID 40888184, 2025). "Interestingly, HPV‐positive cervical cancer cell lines, such as HeLa (HPV18) and CaSki (HPV16), portray high CD44 expression." (PMID 40888184, 2025). "Therefore, evidence supporting the involvement of CD44 in promoting enhanced immune evasion potential through the upregulated expression of both PD-L1 and CTLA-4 in cervical cancer cells is evident." (PMID 38816670, 2024). "In cervical cancer, CAFs and B cells communicate through MIF-(CD74+CXCR4) and MIF-(CD74+CD44)." (PMID 38157264, 2023). "CD44 and ALDH1A1 are both considered to be typical CSC surface markers that can be used alone or in combination with other markers to isolate or enrich CSCs in a variety of tumor types including cervical cancer." (PMID 35860042, 2022). "Adherent cells and tissue sections from invasive cervical cancer showed diffuse positivity for CD44 and were absent in tumorsphere derived cells." (PMID 29609538, 2018). "To assess whether HOXA11-AS promotes CSC generation, we treated the CaSki and HeLa cervical cancer cells for 5 days, and counted the number of cells expressing the CSC markers CD133+/CD44+." (PMID 27792998, 2016). "Lymph node metastatic cervical cancer cells utilize FAO-derived acetyl Co-A to increase histone H3K27 acetylation at the promoters of stemness genes, as well as enhance the expression of pluripotency-related transcription factors (SOX2, OCT4, and NANOG) and the cervical cancer stem cell marker CD44." (PMID 41219902, 2025).
cervical carcinoma (continued). "Therefore, while resveratrol demonstrates HPV‐independent anticancer activity, its dual ability to modulate both general tumor biology and CD44‐mediated CSC pathways positions it as a promising option for targeted interventions, especially in HPV‐driven, CD44‐positive cervical cancers." (PMID 40888184, 2025). "The aim of this review is, therefore, to evaluate whether the pathological effects of CD44-induced metastasis, epithelial-to-mesenchymal transition (EMT), and chemoresistance within cervical cancer patients can be blunted by immune checkpoint inhibition therapy." (PMID 38816670, 2024). "Combined with the existing reports and the results of RNA-seq alternative splicing analysis, it is speculated that GBP1 may regulate the alternative splicing of CD44 protein by binding to interacting protein-HNRNPK, and thus play a role in promoting cancer in cervical cancer." (PMID 38167153, 2024). "Therefore, this review aims to assess whether immune checkpoint inhibition can mitigate the pathological effects of CD44-induced EMT, metastasis, and chemoresistance in cervical cancer patients." (PMID 38816670, 2024). "In cervical cancer, HOXA11-AS silencing was shown to decrease the expression of matrix metalloproteinase-2 (MMP-2), MMP-9, and vascular endothelial growth factor and increase the number of CD133+CD44+ cells, indicating an increase in the cancer stem cell population." (PMID 31757938, 2019).
lymph node metastasis (61 papers, 2005 to 2025). "Further validation using TCGA clinical data confirmed PARD6G-AS1 hypomethylation and CD44 overexpression as significant indicators of recurrence (p=0.006 and p=0.02, respectively), and both were linked to advanced stage and lymph node metastasis." (PMID 40357366, 2025). "High beta-catenin expression was observed to have a significant correlation with a higher T stage (p = 0.006) and TNM staging (p = 0.005), while high CD44 expression was found to be associated with lymph node metastasis (p = 0.01)." (PMID 37012965, 2023). "High beta-catenin expression was observed to have a significant correlation with higher T stage (p = 0.006) and TNM staging (p = 0.005), while high CD44 expression was found to be significantly associated with lymph node metastasis (p = 0.01)." (PMID 37012965, 2023). "These were further supported by analyzing clinical samples, where higher CD44 expression was associated with lymph node metastasis." (PMID 35629265, 2022). "The presence of CD45-EpCAM+CD44+CD24-N-cadherin- cells in NST patients is associated with lymph-node metastasis." (PMID 32316333, 2020). "This is also the first assessment of CD44 expression in curettage specimens as a means to identify patients at increased risk of lymph node metastases and recurrence." (PMID 25129125, 2015). "Multivariate Cox proportional hazard model analysis showed the strong statistical association between CD44 expression and lymph node metastasis." (PMID 26666511, 2015). "In this study, we found the association of increased CD44 protein expression with aggressive tumor-related features, including advanced stage, grade, and lymph node metastasis." (PMID 25889325, 2015). "The incidence of CD44-positive CTCs was significantly associated with tumor location, lymph node metastasis, distant metastasis, and recurrence of GC (P = 0.027, P = 0.033, P = 0.033 and P = 0.011, resp)." (PMID 24963492, 2014). "CD44 amplification was significantly positively associated with lymph node metastasis (OR = 2.23, 95% CI = 1.05–4.73, P < 0.05)." (PMID 22606006, 2012). "Increased CD44 v3 expression in primary tumors was associated with lymph node metastasis, while CD44 v10 expression was associated with distant metastasis and CD44 v6 expression was associated with perineural spread." (PMID 21076545, 2011). "A high expression of CD44 was significantly associated with lymph node metastasis." (PMID 37012965, 2023). "Notably, the elevated CD44 expression was found to be associated with lymph node metastasis in our OSCC cohorts (p = 0.040)." (PMID 35629265, 2022). "Loss of CD44 expression in invaded area is a good indicator of lymph-node metastasis in CRC." (PMID 24185040, 2013). "Moreover, our data also showed that CD44 amplification was significantly positively associated with the number of lymph node metastasis (OR = 1.70, 95% CI = 1.08–2.69, P < 0.05)." (PMID 22606006, 2012). "CD44 overexpression was also significantly associated with FIGO stage III/IV and lymph node metastasis (P = 0.014 and 0.013, respectively)." (PMID 40357366, 2025). "Multiplex immunohistochemistry (mIHC) staining of 4 MISs (CD44, S100A14, RHOD, and TACSTD2) in ESCC clinical samples demonstrated differential MIS expression scores (dMISs) predict lymph node metastasis, overall survival, and risk of carcinothrombosis." (PMID 38864342, 2024). "The CD44 population is responsible for poor differentiation, lymph node metastasis, and distant metastasis." (PMID 39502780, 2024). "In SCC, the CD44v6, an isoform of CD44, reported a positive correlation with the development of lymph node metastasis, although the clinical significance remains controversial." (PMID 37445908, 2023). "Expression of E-cadherin, beta-catenin, and CD44 with respect to grading, staging, lymph node metastasis, and lymphovascular invasion." (PMID 37012965, 2023).
lymph node metastasis (continued). "Our results corroborate the findings in previous studies establishing that presence of CD44 was correlated with treatment failure, lymph node metastasis, advanced stage, tumor size, grade, recurrence, and poor survival." (PMID 35274800, 2022). "CD44 expression was correlated with advanced T stage (OR = 1.76, P = 0.029) and lymph node metastasis (OR = 4.09, P < 0.001)." (PMID 32434417, 2020). "In CRC, CD44 overexpression is related to poor differentiation, lymph node metastasis and distant metastasis." (PMID 32158358, 2020). "Studies have been revealed that overexpression of the CD44 variant exon 6 is associated with tumor differentiation, clinical TNM stage, and lymph node metastasis in patients with NSCLC." (PMID 32344833, 2020). "Expression of AQP3 and that of CD44 positively correlated with Lauren classification, lymph node metastasis, and lymphovascular invasion." (PMID 26918728, 2016). "CD44 expression also correlated significantly with Lauren classification (P = 0.002), lymph node metastasis (P = 0.049), and lymphovascular invasion (P = 0.044)." (PMID 26918728, 2016). "In a multivariable Cox proportional hazard model, which included lymph node metastasis, clinical stage, CD44 expression, and nerve invasion, CD44-positive tumors and lymph node metastasis independently predicted poor prognosis." (PMID 26666511, 2015). "CD44, MMP7 and β-catenin expression was positively associated with distant metastasis, lymph node metastasis and tumor-node-metastasis (TNM) stage." (PMID 26408312, 2015). "For more detailed analysis, we compared between the patients with CD44-positive and lymph node metastasis." (PMID 26666511, 2015). "Many articles have proved that CD44 was closely related with lymph node metastasis, which was well supported by our report." (PMID 26666511, 2015). "The Cox proportional hazard model showed that CD44 and lymph node metastasis were independent prognostic factors." (PMID 26666511, 2015). "CD44-positive tumors were more likely associated with T stage (P = 0.035), TNM staging (P = 0.002), and lymph node metastasis (P = 0.011),which suggested that overexpression of CD44 correlated with a more aggressive phenotype in pancreatic head cancer." (PMID 26666511, 2015). "Cox’s regression analysis was performed using surgical stage, lymph-node metastasis, residual lesion size, CD44 expression, CD47 expression and c-met expression as the dependent variables and survival time as the independent variable." (PMID 25658794, 2015). "Patients whose tumors overexpressed CD44 and lymph node metastasis (LMN) had significantly poorer survival than CD44 and LMN groups (P = 0.001)." (PMID 26666511, 2015). "Our study showed that P-LVD, but not I-LVD, was significantly correlated with lymph vascular space invasion (LVSI), lymph node metastasis, tumor stage, and CD44 expression in endometrial carcinoma." (PMID 20374665, 2010). "Our findings demonstrated that the high expression of CD44 was a predictor of lymph node metastasis and that high ALDH1 immunostaining was associated with angiolymphatic invasion, showing that CD44 and ALDH1 play an important role in OSCC invasion and metastasis." (PMID 38126564, 2023). "The results also suggest that except for CD44 there could be other factors such as lymph node metastasis, grade, and alcohol which should be investigated as potential targets for therapy." (PMID 35274800, 2022). "Simonetti's study demonstrated that IMPC had high expression of CD24 and low expression of CD44 compared with IDCs, which might explain the increased propensity for lymph node metastasis." (PMID 31839814, 2019). "The results of our report supported that the function of the lymph node metastasis might be dependent on CD44." (PMID 26666511, 2015).